UBIAD1 (UbiA prenyltransferase domain containing 1)
Description:
Prenyltransferase that mediates the formation of menaquinone-4 (MK-4) and coenzyme Q10. MK-4 is a vitamin K2 isoform present at high concentrations in the brain, kidney and pancreas, and is required for endothelial cell development. Mediates the conversion of phylloquinone (PK) into MK-4, probably by cleaving the side chain of phylloquinone (PK) to release 2-methyl-1,4-naphthoquinone (menadione; K3) and then prenylating it with geranylgeranyl pyrophosphate (GGPP) to form MK-4. Also plays a role in cardiovascular development independently of MK-4 biosynthesis, by acting as a coenzyme Q10 biosynthetic enzyme: coenzyme Q10, also named ubiquinone, plays an important antioxidant role in the cardiovascular system. Mediates biosynthesis of coenzyme Q10 in the Golgi membrane, leading to protect cardiovascular tissues from NOS3/eNOS-dependent oxidative stress.
Synonyms: TERE1; SCCD
Tractability: Antibody: UniProt predicts a signal peptide or a membrane-spanning region. PROTAC: ubiquitination databases record sites on it; its protein half-life has been measured.
Gene: Protein-coding gene on chromosome 1 (11,273,198 to 11,296,049, forward strand). Ensembl gene ENSG00000120942.
Subcellular location: Endoplasmic reticulum membrane; Golgi apparatus membrane; Mitochondrion membrane; Cytoplasm; Nucleus
Subcellular location (Human Protein Atlas): Vesicles
Pathways (Reactome):
Metabolism: Metabolism of vitamin K
Gene Ontology:
Molecular function: antioxidant activity; menadiol geranylgeranyltransferase activity; prenyltransferase activity; protein binding; 4-hydroxybenzoate polyprenyltransferase activity; transferase activity, transferring alkyl or aryl (other than methyl) groups
Biological process: menaquinone biosynthetic process; ubiquinone biosynthetic process; vitamin K biosynthetic process; vitamin K metabolic process; cellular oxidant detoxification
Cellular component: cytoplasm; endoplasmic reticulum; endoplasmic reticulum membrane; Golgi membrane; membrane; mitochondrial membrane; nucleus; endomembrane system
Genetic constraint (gnomAD): Loss-of-function variants: 12 observed, 21.13 expected, observed/expected ratio (o/e) 0.57, 90% interval 0.36 to 0.92. The upper end of that interval is the gene's LOEUF score, 0.92, which puts it in group 3 of 6, group 1 being the genes least tolerant of losing a copy. Missense variants: 333 observed, 445.57 expected, observed/expected ratio (o/e) 0.75, 90% interval 0.68 to 0.82. Synonymous variants: 207 observed, 203.12 expected, observed/expected ratio (o/e) 1.02, 90% interval 0.91 to 1.14.
Homologues: Orthologues: chimpanzee UBIAD1 (99% identical), macaque UBIAD1 (99% identical), pig UBIAD1 (93% identical), guinea pig UBIAD1 (92% identical), mouse Ubiad1 (92% identical), rat Ubiad1 (92% identical), dog UBIAD1 (89% identical), tropical clawed frog ubiad1 (78% identical), zebrafish ubiad1 (70% identical), Drosophila melanogaster heix (52% identical).
Diseases named in the same sentence as UBIAD1 in open-access papers:
UBIAD1 is named in the same sentence as 59 diseases in open-access papers, as found by Europe PMC text mining. Sharing a sentence is not in itself a finding about the gene and the disease. The quoted sentences say what the papers report.
Schnyder corneal dystrophy (32 papers, 2007 to 2024). Schnyder corneal dystrophy (SCD) is a rare form of stromal corneal dystrophy characterized by corneal clouding or crystals within the corneal stroma, and a progressive decrease in visual acuity. "Due to UBIAD1 mutations, schnyder corneal dystrophy (SCD) induces the over production of cholesterol in the cornea." (PMID 35379328, 2022). "Other abnormalities included microphthalmia in 2/14 patients (14.3%) and corneal opacities in 2/14 patients (although one patient had also been diagnosed with Schnyder’s corneal dystrophy secondary to a concomitant mutation in UBIAD1)." (PMID 33562844, 2021). "Mutations in the gene encoding UbiA prenyltransferase domain-containing protein-1 (UBIAD1) cause Schnyder corneal dystrophy (SCD), a rare autosomal dominant eye disease characterized by opacification of the cornea." (PMID 30785396, 2019). "Consistent with cholesterol synthesis as a source of accumulated cholesterol in the cornea, mutation of the UBIAD1 gene causes Schnyder corneal dystrophy, which results in corneal clouding due to accumulation of extracellular lipid deposits." (PMID 31779197, 2019). "Enzymatic analysis using site-directed mutagenesis revealed that UBIAD1 is capable of generating various MKs, including MK-4; additionally, UBIAD1 missense mutations were found to significantly lower MK-4 biosynthetic activity in Schnyder corneal dystrophy." (PMID 31013667, 2019). "Schnyder corneal dystrophy (SCD) is an autosomal dominant disease in humans caused by mutations in the UBIAD1 gene." (PMID 29977031, 2018). "In summary, we report the first de novo mutation in UBIAD1 associated with Schnyder corneal dystrophy." (PMID 27382485, 2016). "Schnyder corneal dystrophy (SCD) has been associated with 25 different mutations in UBIAD1 in the 54 families in which screening has been reported to date." (PMID 27382485, 2016). "Schnyder corneal dystrophy is caused by dominant mutant forms of UBIAD1 (UbiA prenyltransferase domain‐containing protein‐1) but how perturbation of UBIAD1 function leads to cholesterol buildup is unclear." (PMID 27329485, 2016). "In humans, mutations in UBIAD1 cause a rare autosomal-dominant eye disease called Schnyder corneal dystrophy (SCD)." (PMID 25127365, 2014). "UBIAD1 has been shown to be an important disease-related protein in both dyslipidemia associated SCD (Schnyder’s corneal dystrophy) and bladder carcinoma." (PMID 23977195, 2013). "Ubiad1 (UbiA prenyltransferase domain containing 1) encodes a class of UbiA prenyltransferase involved in SCD (Schnyder’s corneal dystrophy), a rare dominant genetic eye disease." (PMID 23977195, 2013). "The identification of five different segregating, rare missense variants in an extremely conserved gene, strongly supports the identification of UBIAD1 as the causal gene for Schnyder crystalline corneal dystrophy." (PMID 17668063, 2007). "The physiologic significance of the UBIAD1-HMGCR interaction is confirmed by the observation that missense mutations in UBIAD1 cause Schnyder corneal dystrophy (SCD), an autosomal-dominant eye disease characterized by corneal opacification owing to the over-accumulation of cholesterol." (PMID 35879350, 2022). "Genetic mutations in ABCA1 (Tangier disease), LCAT (familial lecithin:cholesterol acyltransferase deficiency), ApoA1 (familial apolipoprotein (Apo) A1 deficiency), and UBIAD1 (Schnyder corneal dystrophy, SCD) all result in corneal accumulation of lipids including cholesterol." (PMID 34547023, 2021). "Furthermore, the experiments show that the genetic mutations linked to Schnyder corneal dystrophy lead to the production of versions of the UBIAD1 protein that bind to the reductase enzyme even when geranylgeraniol molecules are present." (PMID 25742604, 2015). "Clinical studies identified missense mutations in human UBIAD1 that cause the autosomal-dominant eye disease Schnyder Corneal Dystrophy (SCD)." (PMID 36275615, 2022).
Schnyder corneal dystrophy (continued). "Missense mutations in the UBIAD1 gene cause Schnyder corneal dystrophy (SCD), an autosomal dominant eye disease in humans characterized by the corneal accumulation of cholesterol." (PMID 34842525, 2021). "The function of UBIAD1 appears to extend beyond its role in MK-4 synthesis, as indicated by association of mutations in human UBIAD1 with Schnyder corneal dystrophy (SCD)." (PMID 32118581, 2020). "Missense mutations in UBIAD1 are the underlying cause of the human genetic disorder Schnyder corneal dystrophy (SCD)." (PMID 25874989, 2015). "Missense mutations to the UBIAD1 gene are the underlying cause of the genetic disorder Schnyder corneal dystrophy (SCD), which causes accumulation of cholesterol and phospholipids in the cornea of the eye, eventually leading to blindness." (PMID 25051182, 2014). "Mutations in a novel gene, UBIAD1, were recently found to cause the autosomal dominant eye disease Schnyder corneal dystrophy (SCD)." (PMID 20505825, 2010). "Ultrastructurally, the lipid in Schnyder corneal dystrophy (defective UBIAD1) also accumulates as extracellular membranous and vacuolar structures like that seen in LCAT deficiency, but additionally within cholesterol crystals in about half the cases." (PMID 31779197, 2019). "Schnyder corneal dystrophy mutant UBIAD1 interferes with sterol-induced HMGCoA reductase degradation resulting in elevated cholesterol synthesis in vitro." (PMID 31779197, 2019). "Schnyder corneal dystrophy (SCD) is a rare autosomal dominant disease in humans, characterized by abnormal deposition of cholesterol and phospholipids in cornea caused by mutations in the UbiA prenyltransferase domain containing 1 (UBIAD1) gene." (PMID 29977031, 2018). "Schnyder corneal dystrophy (SCD; OMIM #121800) is a rare autosomal dominant disease classified within the group of stromal dystrophies (IC3D 2015,) and caused by UBIAD1 pathogenic variants." (PMID 30084067, 2018).
bladder cancer (11 papers, 2007 to 2023). "Low expression of UBIAD1 in human breast tumours correlates with reduced survival and also associates with risk for bladder cancer." (PMID 37410739, 2023). "UbiA prenyltransferase domain-containing protein 1 (UBIAD1) is downregulated by exosomal miRNA-4644 via binding to its 3’-UTR to enhance bladder cancer cell invasion." (PMID 35765040, 2022). "UBIAD1 inhibited H-Ras trafficking from the Golgi apparatus to the plasma membrane and inhibited the proliferation of bladder cancer cells." (PMID 30518913, 2018). "As UBIAD1 suppresses bladder carcinoma, we studied its subcellular localization in human bladder carcinoma cell line T24." (PMID 23977195, 2013). "Using a combination of biochemical and cellular approaches, we found in the present study that UBIAD1 accumulates on the Golgi in human bladder carcinoma cell line T24." (PMID 23977195, 2013). "We showed that UBIAD1 is a transmembrane protein that accumulates on the Golgi apparatus of human bladder carcinoma cells." (PMID 23977195, 2013). "As UBIAD1 is a bladder carcinoma suppressor, it is reasonable to presume that the subcellular localization of UBIAD1 on the Golgi is related to its tumor suppressing function." (PMID 23977195, 2013). "Mutation of Arginine 54 (R54) to Alanine disrupts the Golgi localization of the mutant proteins (AAAA and APWS) in T24 cells, indicating that RPWS motif also serves as the Golgi retention signal for UBIAD1 in bladder carcinoma T24 cells." (PMID 23977195, 2013). "In this paper, we examined the subcellular localization of UBIAD1 in human bladder carcinoma cell line T24 as well as in human prostate cancer cell line PC-3, human embryonic kidney cell line HEK293 and human hepatocyte cell line L02." (PMID 23977195, 2013). "In both cases, UBIAD1 proteins were observed to colocalize with the Ds Red-Golgi marker, indicating that at least a portion of the UBIAD1 proteins is localized on the Golgi in human bladder carcinoma cells." (PMID 23977195, 2013). "Ubiad1, also known as Tere1 (transitional epithelial response gene), was first cloned as a tumor suppressor for human bladder carcinoma." (PMID 23977195, 2013). "It seems that the addition of UBIAD1 induces apoptosis of bladder carcinoma T24 cells with percentages of late apoptosis cells (B2) increasing from 11.9% (MC, mock control, T24 cells with Lipofectamine only) to 29.6%." (PMID 23977195, 2013). "The discrepancy between different reports of UBIAD1 subcellular localization compelled us to further investigate this issue in bladder carcinoma cells as UBIAD1 has been shown to be a tumor suppressor for bladder carcinoma." (PMID 23977195, 2013). "Bladder carcinoma T24 cells were transfected with wild type UBIAD1 and UBIAD1 RPWS→AAAA mutant (with RPWS changed to AAAA) with no GFP attached." (PMID 23977195, 2013). "In conclusion, UBIAD1 is localized on the ER and the Golgi in human bladder carcinoma cells T24." (PMID 23977195, 2013). "UBIAD1 could inhibit the proliferation of bladder cancer cells via interaction with H-Ras35." (PMID 34211100, 2021). "Of particular interest, UBIAD1 was previously identified as TERE-1, a tumor suppressor gene originally identified in prostate and bladder cancers." (PMID 31040920, 2019). "UbiA prenyltransferase domain containing 1 (UBIAD1), also known as transitional epithelial response gene (TERE1), was first identified in 2001 as a tumor suppressor for human bladder carcinoma." (PMID 26890002, 2016). "Here, we report that UBIAD1 interacts with H-Ras, increases the retention of H-Ras in the Golgi apparatus, inhibits the aberrant activation of Ras/ERK signaling at the plasma membrane and consequently suppresses the proliferation of bladder cancer cells." (PMID 30518913, 2018).
bladder cancer (continued). "UBIAD1 plays critical roles in physiology including vitamin K and CoQ10 biosynthesis as well as pathophysiology including dyslipimedia-induced SCD (Schnyder’s corneal dystrophy), Parkinson’s disease, cardiovascular disease and bladder carcinoma." (PMID 23977195, 2013). "This study show that UBIAD1 interacts with H-Ras, retains H-Ras in the Golgi apparatus, prevents H-Ras trafficking from the Golgi apparatus to the plasma membrane, blocks the aberrant activation of Ras/MAPK signaling, and inhibits the proliferation of bladder cancer cells." (PMID 30518913, 2018).
corneal dystrophy (8 papers, 2007 to 2020). The term corneal dystrophy embraces a heterogeneous group of bilateral genetically determined non-inflammatory corneal diseases that are usually restricted to the cornea. "Although mutations in genes such as KRT3, KRT12, PIP5K3, TGFBI, and UBIAD1 have been associated with specific corneal dystrophies, genes associated with all corneal dystrophies have yet to be identified." (PMID 32823625, 2020). "Studies of the genetic basis of the corneal `dystrophies have revealed that most reported cases of SCCD are caused by amino acid substitutions within UBIAD1, and most reported mutations have been missense mutations." (PMID 19649163, 2009). "Despite the rarity of this corneal dystrophy, the fact that affected Chinese family also has mutation in UBIAD1 provides another evidence to support the hypothesis that SCCD is possibly caused by UBIAD1 mutations." (PMID 19649163, 2009).
prostate carcinoma (6 papers, 2013 to 2022). A carcinoma that arises from epithelial cells of the prostate gland. "UBIAD1 has been known as a tumor suppressor for urological cancer, castrate-resistant prostate cancer and renal cell carcinoma." (PMID 36275615, 2022). "UBIAD1 (also known as transitional epithelial response protein 1 (TERE1)) suppressed the proliferation of transitional cell carcinoma cell lines and prostate cancer cell lines." (PMID 25127365, 2014). "Since UBIAD1 has been shown to affect the growth of human prostate cancer cell line PC-3, PC-3 cells were used to study the subcellular localization of UBIAD1 as well." (PMID 23977195, 2013). "UBIAD1 colocalizes with the Golgi in human prostate cancer cell line PC-3." (PMID 23977195, 2013). "UBIAD1, also known as transitional epithelial response protein 1 (TERE1), suppresses the proliferation of transitional cell carcinoma cell lines and prostate cancer cell lines." (PMID 25874989, 2015). "Since fluorescent images of UBIAD1-EGFP in T24, human prostate cancer cell line PC-3, human embryonic kidney cell line HEK293 and human hepatocyte cell line L02 are similar, these four cell lines were used for present study." (PMID 23977195, 2013).
macular corneal dystrophies (3 papers, 2019 to 2023). "For example, direct correlations have been established between mutations in CHST6, UBIAD1, SLC4A11, PIKFYVE, TACSTD2, and DCN with macular corneal dystrophies (MCD), Schnyder CD, congenital hereditary endothelial dystrophy, fleck CD, gelatinous drop-like CD, and congenital stromal CD, respectively." (PMID 31555324, 2019).
melanoma (3 papers, 2018 to 2022). A malignant, usually aggressive tumor composed of atypical, neoplastic melanocytes. "•UBIAD1 is associated with poor overall survival (OS) of melanoma patients and is highly expressed in melanoma cell lines." (PMID 35255427, 2022). "Concerning melanoma, high UBIAD1 mRNA level is associated with poor prognosis (OS) in melanoma patients based on TCGA-Skin Cutaneous Melanoma datasets." (PMID 35255427, 2022). "Here, we provide evidence that UBIAD1 expression is associated with poor overall survival (OS) in human melanoma patients." (PMID 35255427, 2022). "When melanoma cells experience UBIAD1/CoQ10/NQO1 loss, ROS levels increase and promote lipid peroxidation as well as apoptotic cell death." (PMID 35255427, 2022). "SkMel28 and A375 melanoma cells were TUNEL-positive after UBIAD1KD with UBIAD1 loss leading to apoptotic cell death in a dose-dependent manner." (PMID 35255427, 2022). "Since our co-localization studies showed that UBIAD1 is mostly present in Golgi apparatus in BRAF-mutated melanoma cells, we examined CoQ10 levels after UBIAD1KD in SkMel28 and A375 cells and we found them to be significantly reduced, as expected." (PMID 35255427, 2022). "We observed a significant expression of UBIAD1 protein in most of the melanoma cells tested, with BRAF-mutated cell lines (except for RPMI-7951) showing the highest amount of UBIAD1." (PMID 35255427, 2022). "Remarkably, UBIAD1 loss promotes lipid peroxidation in all tested melanoma cells lines." (PMID 35255427, 2022). "To explore whether UBIAD1 deficiency induces lipid peroxidation in melanoma cells, we performed lipid peroxidation analyses using Bodipy C11 581/591 on SkMel28, A375 and Mel Juso cells after UBIAD1KD." (PMID 35255427, 2022). "We then knocked-down UBIAD1 (UBIAD1KD) in these cell lines and performed a growth curve assay to determine whether UBIAD1 loss could affect melanoma proliferation." (PMID 35255427, 2022). "By showing that the CoQ10-producing enzyme UBIAD1 counteracts oxidative stress and lipid peroxidation events in cutaneous melanoma, this work may open to new therapeutic investigations based on UBIAD1/CoQ10 loss to cure melanoma." (PMID 35255427, 2022). "To determine the functional role of UBIAD1 in melanoma progression we first tested mRNA and protein levels of UBIAD1 in a panel of melanoma cell lines and observed that UBIAD1 is significantly upregulated in melanoma cells with respect to melanocytes." (PMID 35255427, 2022). "In this study, we showed that UBIAD1, a transmembrane enzyme localized in the Golgi apparatus, plays a key role in suppressing lipid peroxidation and promoting melanoma survival through CoQ10 synthesis and NQO1-dependent plasma membrane redox regulation." (PMID 35255427, 2022). "Overall, we conclude that UBIAD1 and CoQ10 are significantly expressed during melanoma progression as well as in melanoma cells carrying both BRAF and NRAS mutations." (PMID 35255427, 2022). "•NQO1 is required for UBIAD1/CoQ10-mediated melanoma lipid peroxidation protection and cell survival." (PMID 35255427, 2022). "Here we show for the first time that UBIAD1 plays an antioxidant tumor-promoting role in melanoma cells by supporting plasma membrane CoQ10 synthesis and, thus, contributing to protect membrane components against lipid peroxidation and cell death." (PMID 35255427, 2022). "The purpose of this study is to demonstrate that UBIAD1 is essential for melanoma survival by providing antioxidant protection through CoQ10 synthesis." (PMID 35255427, 2022). "In summary, we suggest that NQO1 protein is responsible for CoQ10 redox regeneration downstream of the UBIAD1/CoQ10 axis in melanoma cell lines." (PMID 35255427, 2022). "We conclude that NQO1 is located downstream of UBIAD1 and cooperates with it to protect BRAF-mutated melanoma cells from lipid peroxidation and cell death." (PMID 35255427, 2022).